CXCR3 (C-X-C motif chemokine receptor 3)
Diseases named in the same sentence as CXCR3 in open-access papers (continued):
Sharing a sentence is not in itself a finding about the gene and the disease.
infection (continued). "Here, we investigated the role of CXCR3 in recruitment of leukocytes and T cells during the early stage of infection (5 dpi)." (PMID 36704563, 2022). "The significant increase in CXCR3+ γδ T cells in our study at 1-7dpi in aerosol infection in contrast to IT/IN infection, indicated an impaired ability of Vδ1 T cells to traffic to sites of inflammation during early stages of IT/IN infection." (PMID 36526890, 2022). "Nonetheless, neutrophils also appear to be essential for the early formation of pulmonary granulomas in response to infection with Mtb via the induction of CXCR3-signalling chemokines." (PMID 36139450, 2022). "CXCR3 was found to be a key player in the migration of these cells to the infection site, as evidenced by increased parasite load and subsequent death of mice treated with anti-CXCR3." (PMID 35794867, 2022). "To further interrogate preferential infection of CXCR3+ Tfh cells, we used a broadly neutralizing antibody called 3BNC117 to stain HIV-infected cells expressing the HIV envelope protein (gp120), while simultaneously staining for CXCR3." (PMID 35831418, 2022). "CXCR3 aids in the recruitment of CD8+ T cells to the site of infection, a widespread defense mechanism of the host against viruses." (PMID 35794867, 2022). "This, in turn, promoted CXCR3-dependent accumulation of BRM cells within sites of infection where they quickly differentiated into PCs." (PMID 35349789, 2022). "Surprisingly, not all Unconventional T cells, such as MAIT cells, recovered their ability to produce IFN-γ and the expression of CXCR3 after infection though maintained CD69 and PD1 expressed." (PMID 35159352, 2022). "Infection of enriched peripheral blood B cells with the B95-8 EBV strain led to the development of a CD19+/CXCR3+/CD11c+ cell population within five days in vitro." (PMID 36248899, 2022). "Tregs up-regulate CXCR3 in response to the infection, which directs them to the lung as the site of an ongoing immune response." (PMID 35572535, 2022). "We injected IfnbYFP/YFP mice at the time of infection both with anti-CXCR3 (CXCR3-173 clone) and anti-CXCL9 2A6.9.9 mAb, which blocks the CXCL10-binding site and neutralizes soluble CXCL9, respectively." (PMID 36278864, 2022). "The transcriptional changes upon infection were dominated by Ifng and its downstream genes (e.g. Stat1, Irf1, Fcgr1, Nos2, Cxcr3) and IFN-dependent CXCR3 binding chemokines (e.g. Cxcl9, Cxcl10)." (PMID 36400767, 2022). "These T cells all expressed CXCR3 as the infection progressed, and exhibited an activated CD44+CD62L− profile by day 7 p.i.." (PMID 34707143, 2021). "CXCR3 is associated with the recruitment of both CD4+ and CD8+ T cells to the site of infection, IFN-γ secretion from the T cells, and the resultant activation of inflammatory monocytes." (PMID 34835465, 2021). "These NK cells express increased CXCR3 and Ki67, indicating their recruitment and proliferation subsequent to znBAZ infection." (PMID 34305935, 2021). "For example, CXCR3 activation can affect the proliferation and immune responses of macrophages and dendritic cells during infection with Leishmania amazonensis." (PMID 34835465, 2021). "After 30 days of infection, CXCR3+CCR5+CCR4+ CD8+ T-cells were predominant in the blood (Student’s t-test, p = 0.001), as reported for CD4+ T-cells." (PMID 34685494, 2021). "Compared with B6 mice, we found in pMT-10 mice that ESAT-61–20–specific CD4+ T cells from the lungs displayed reduced expression of CXCR3 at days 24 and 31 after infection." (PMID 34554927, 2021). "Analysis of lung NK cells two days post-infection reveals that these are CXCR3+ and exhibit the Ki67 proliferation marker, suggesting that znBAZ infection induces early NK cell infiltration and then, proliferation." (PMID 34305935, 2021). "CXCR3 also controls the recruitment of microglia to the infection sites and enhances proliferation of epithelial cells." (PMID 34835465, 2021).
infection (continued). "On the third day after infection, CXCR3+CXCR6+ γδT cells showed significantly higher expression of Ki67, indicating that the proliferative capacity of CXCR3+CXCR6+ γδT cells was enhanced postinfection." (PMID 35126348, 2021). "CXCL9/CXCR3 can chemotaxis and recruit macrophages and T cells to the site of infection during the invasion of HP." (PMID 33763365, 2021). "Overall, we have demonstrated that C57BL/6 mice died very quickly due to infection during the anti-CXCR3 treatment." (PMID 32574175, 2020). "CXCR3-mediated T cell migration has been reported to be important to clear infections in other contexts, including infections by epicutaneous vaccinia virus, protozoan parasite Toxoplasma gondii, and herpes simplex virus type 2." (PMID 31968015, 2020). "Here, we showed that by recruiting CXCR3+ Tregs, MSC treatment restricted the overactivation of inflammatory responses and prevented severe symptoms caused by infection." (PMID 33014369, 2020). "During infection with HSV-2, T cells from CXCR3-deficient mice exhibited impaired CD8+ T cell cytotoxicity and reduced expression of T-bet, IFN-γ, perforin and granzyme B." (PMID 32574175, 2020). "In fact, we demonstrated that CXCR3 guides CD8+ T cells to the heart after infection with T. cruzi, since we observed a decreased in the frequency of those cells after anti-CXCR3 antibody treatment." (PMID 32574175, 2020). "CXCL10 is a pro-inflammatory Th1-chemokine driving migration to the site of infection of Th-1 T-cells, monocytes and neutrophils that express its receptor CXCR3." (PMID 33272291, 2020). "We showed that, in addition to CCR6+ CD27– γδ T cells, the numbers of CCR6–CD27– γδ T cells increased along with their CXCR3 and IL‐17A expression during infection." (PMID 31777067, 2020). "Tetramer labeling revealed enrichment of resident memory CD4+ T (Trm) cells in the lower airway; these Trm cells displayed progressive differentiation, downregulation of costimulatory molecules, and elevated CXCR3 expression as infection evolved." (PMID 31815739, 2020). "The expression of these CXCR3 chemokines increased up to 42 days after infection with Mtb and remained at this level." (PMID 33375150, 2020). "One example was an infection-induced interaction between myeloid cells and T cells via Cxcl9 and Cxcr3." (PMID 32461220, 2020). "Initially, we evaluated the number of specific CD8+ T cells in spleen after anti-CXCR3 treatment on day 15 after infection." (PMID 32574175, 2020). "Of those chemokine receptors, only a slight increase in the percentage of CXCR3-expressing MAIT cells was observed after infection, and this only occurred in the thymus (P < 0.05)." (PMID 32849637, 2020). "We further demonstrated that, following lethal infection, CXCR3-dependent recruitment of effector ZIKV-specific CD8 T cells to the CNS is important for efficient control." (PMID 32973802, 2020). "The role of CXCR3 in T cell migration has been demonstrated during infection by Toxoplasma gondii: CXCR3+ CD4+ T migrated into infected tissues and controlled the infection." (PMID 32574175, 2020). "The chemokine CXCL10 (IP-10) plays a deleterious role in infection and inflammation by activating the chemokine receptor CXCR3, an important regulator of lymphocyte trafficking and activation." (PMID 32973504, 2020). "In our study, reduced expression of IFNγ, LTα, ICAM-1, CXCL9 and CXCL10 were in line with impaired recruitment of CXCR3+CD8+ T cells to the brains of mice that received BCG before PbA infection." (PMID 33316929, 2020). "Upregulation of Th1 and M1 macrophage activation markers like Ifng, Stat1, Cxcl9, Cxcl10, Ccr5, Cxcr3, Xcl1, and Ccl3 occurs in early infection." (PMID 31635276, 2019). "Here, we evaluated the cytotoxicity activity of TEWETGQI-specific CD8+ T-cells after treatment with anti-CXCR3 antibody after immunization and infection." (PMID 31356587, 2019). "The results implicate CD103+ DCs in the trafficking of CXCR3+ Tbet+ T-cells to sites of infection and tumorigenesis." (PMID 31188899, 2019).
infection (continued). "The role of CXCR3 in the resistance against infections by virus and other pathogens has been shown, reinforcing that CXCR3 is essential to control infection by intracellular pathogens." (PMID 31356587, 2019). "GP63 cleavage of CXCL10 occurs throughout in vitro infection and abrogates CXCR3-dependent T cell migration." (PMID 31440475, 2019). "CXCR3, through the binding to its ligand IP-10, is an important receptor responsible for the recruitment of NK cells to the site of infection or inflammation." (PMID 31708922, 2019). "Further, we used an anti-CXCR3 blocking antibody as a tool to interfere in the migration process of CD8+ T-cells and analyzed susceptibility to infection, migration pattern, tissue colonization and effector activity." (PMID 31356587, 2019). "Because CXCL10 coordinates the recruitment of CXCR3+ T cells during infection, we next tested if GP63 cleavage of CXCL10 impacts T cell recruitment." (PMID 31440475, 2019). "On the same day of challenge with the Y strain infection, A/Sn mice were treated with the anti-CXCR3 or anti-CCL2 monoclonal antibodies." (PMID 31356587, 2019). "In contrast, the ability of CD4+Foxp3+ Tregs to migrate to CXCR3 chemokines decreased significantly with infection." (PMID 30915078, 2019). "Specifically, transcription of Cxcl10 is upregulated in T resident-memory (Trm) cells after secondary infection, and antibody blockade of CXCR3 prevents recruitment of circulating CD4+ T cells to the site of infection." (PMID 31440475, 2019). "Our results suggest that responding CLA+CXCR3+CCR5+ CD56bright NK cells have the capacity to home to the site of infection (skin) during acute DENV infection." (PMID 31467285, 2019). "Consistent with CXCL10 playing a protective role during infection, multiple studies show that recruitment of CXCR3-expressing cells actively shapes the immune response." (PMID 31440475, 2019). "First, the host upregulates CXCL10 transcription throughout infection and cells expressing CXCR3 are expanded after infection." (PMID 31440475, 2019). "CXCL10 expression is sharply upregulated upon infection and, like fellow chemokine CXCL9, binds receptor CXCR3 expressed on monocytes, NK cells, and T cells to promote their homing to the site of infection." (PMID 30167845, 2018). "We found Treg specialization into T-bet+CXCR3+ Treg cells to be a mutual feature of all three infections but the peak of activation was observed at different time points depending on the infectious setting." (PMID 29951069, 2018). "Upregulation of chemokine receptors such as CXCR3 has been observed with Th1 priming in the lymph node after infection with some respiratory pathogens and has been suggested to play a role into recruitment in the lung after intranasal infection or vaccination." (PMID 29681900, 2018). "In this study, we determined the signature of CXCR3+ Treg cells arising in Th1 settings and defined universal features of Treg cells in this context using multiple Th1-dominated infection models." (PMID 29951069, 2018). "Other inflammatory chemokines, such as CXCL9 and CXCL10, are highly expressed by keratinocytes in response to infection, and facilitate the recruitment of CXCR3+ memory precursor effector CD8+ T cells to the epidermis." (PMID 29904388, 2018). "In lung, CTL migration to infection sites has been shown to be CXCR3 dependent, and this tissue positioning is considered to be one of the rate-limiting steps in CTL-mediated protection." (PMID 29760706, 2018). "As only few of the abundant number of CD4+ T cells at the site of infection express CXCR3, it seems plausible that the CXCL10/CXCR3 chemotactic axis is under regulation by DPP4 in active TB." (PMID 30026741, 2018). "The expansion of virus-specific CD8 T cells in the lung and airways following infection corresponds with an increase in CXCR3- and CCR5-binding chemokines, supporting a role for chemokine-mediated migration of CD8 T cells following secondary infection." (PMID 29686673, 2018).
infection (continued). "RNA-Seq samples were sorted from LCMV-infected mice as the induction of the CXCR3+ Treg subset was strongest in this infection model." (PMID 29951069, 2018). "As shown in, our data indicated that on day 7 post infection, CXCR3−/− mice had significantly less amount of CD4 T cells in Spl and iLN, but not in GT, than WT." (PMID 29552679, 2017). "IL-27 and IFN-γ can also induce a Treg population (T-bet+, CXCR3+) that produce higher IL-10 to limit T effector responses, thus reducing infection-induced pathology." (PMID 29118754, 2017). "Since the bacterial burden of the CXCR3−/− mice was significantly higher during the infection with Chlamydia comparing with WT, we looked further into adaptive immune responses elicited in these two strains." (PMID 29552679, 2017). "In order to examine CXCR3’s influences on leukocyte functions during CM infection, we infected both CXCR3−/− and WT counterpart intravaginally, and identified IFN-γ secreting NK cells, macrophages, and neutrophils by flow cytometry." (PMID 29552679, 2017). "Following chlamydial genital infection, CXCR3 activates cDC and pDC, and directs them to the infection site and activates CD4 and CD8 T cells into functional subsets, including (not only) Th1 cells, CD8TFN-α T cells." (PMID 29552679, 2017). "In this study, we explored the impact of CXCR3 on modulation of host immune responses and infection course following C. muridarum intravaginal challenge using CXCR3−/− mice." (PMID 29552679, 2017). "Together, our data suggest that chemokine CXCR3 is involved in tissue pathology and damage in mouse genital tract after C. muridarum intravaginal infection." (PMID 29552679, 2017). "We found mRNAs of the type 1 chemokine ligands and their receptors (CCL4, CCL5, CCR5, CXCL9, CXCL10, CXCL11 and CXCR3) were increased at 21–28 days post-infection compared to uninfected controls." (PMID 28103263, 2017). "At days 9 and 15, we observed a higher proportion and absolute number of Zbtb32-/- compared to WT P14 cells, as well as a greater proportion of Zbtb32-/- P14 cells expressing the memory markers CD27 and CXCR3 at day 9 post-infection (top)." (PMID 28827827, 2017). "Both the WT and CXCR3−/− mice cleared the CM infection by 27 days post infection; however, the knockout mice possessed a significantly higher bacterial burden on days 3, 6 and 9, when compared to WT mice." (PMID 29552679, 2017). "Through all the locations checked, Th1 T cells, the cell type responsible for clearance of infection, were significantly lower in CXCR3−/− mice than in WT." (PMID 29552679, 2017). "The factors influencing the expression of CXCR3 remain poorly defined, particularly during infection." (PMID 28710387, 2017). "Here we also observed a higher infection rate in the small intestine than in the large intestine, correlating with the IP-10/CXCR3 regionalized expression." (PMID 27509048, 2016). "In our study, we observed a decreased expression of the frequency of CXCR3+ CD56bright NK cells in HCV mono-infection as well as in HIV mono-infection, which was even more pronounced than in HCV mono-infection." (PMID 27091211, 2016). "Our results reveal that CXCR3 is the primary chemokine receptor on CD19+ B cells that persist within the brain following infection." (PMID 27207308, 2016). "Splenic CD4+ YFP+ GFP+ T cells from mice on day 7 of infection were almost universally CXCR3+, whereas they expressed only low levels of CCR1, CCR6, and CXCR6." (PMID 26459508, 2016). "CXCR3-deficient CD8 T cells were able to enter the vaccinia virus-infected dermis, but fewer CD8 T cells entered, or were retained in, the infection foci compared to WT CD8 T cells." (PMID 27790220, 2016). "Though, when we looked at the intestinal mucosa, we found a significant higher rate of infection in the small intestine where the expression of IP-10 and CXCR3 were the highest." (PMID 27509048, 2016).
infection (continued). "Multivariate logistic regression showed a correlation of infection with a cluster containing %CD38+ Ki67− of CXCR5− CXCR3− CCR4+ TEM cells as the only positive coefficient with CD38 expression thus determining the significance." (PMID 27064238, 2016). "Recent studies have shown a high infection rate among CXCR3+ CD4+ T-cells, which are also preferentially enriched for HIV DNA in HIV-infected individuals on cART." (PMID 27509048, 2016). "The prominent and sustained expression of CXCR3 on infiltrating CD19 B cells over the course of infection is consistent with the high-level detection of its ligands CXCL9 and CXCL10 in brain homogenates using ELISA." (PMID 27207308, 2016). "The percentage of T-bet+ CD4+ T cells on day 3 post-infection was increased in the FeD mice, concurring with the increased percentage of CXCR3+ CD4+ T cells observed on this day." (PMID 25768944, 2015). "In this study, we report on the function of CXCR3 signaling in macrophage recruitment to infection foci and in the early establishment of mycobacterial granulomas." (PMID 25573892, 2015). "It is also possible that aberrant expression of homing receptors such as CD62L and Cxcr3 prevents p110δD910A T cells from fully engaging with the relevant APCs during the early stages of their response to infection." (PMID 26311905, 2015). "The upregulation of CXCR3 upon infection in a METH environment has a strong implication that METH can affect CD8 T cell responses as well as generation of memory response." (PMID 26322025, 2015). "Expression of CXCL9 and 10 can be induced by IFN-γ and/or TNFα in several liver resident cells, including hepatocytes, LSECs, HSCs and KCs, promoting further recruitment of CXCR3-expressing cells to the site of infection." (PMID 24646914, 2014). "The chemokine CXCL10 is produced during infection and inflammation to activate the chemokine receptor CXCR3, an important regulator of lymphocyte trafficking and activation." (PMID 24890566, 2014). "The increased induction of C-X-C chemokines, IP-10 in MTb infection attracts Th1-, Tc1-activated lymphocytes and NK cells through CXCR3." (PMID 25135111, 2014). "CXCL10 activates the chemokine receptor CXCR3 and is an important regulator of lymphocyte trafficking in a variety of diseases characterized by infection or inflammation." (PMID 24890566, 2014). "While our study focuses on the early response to Toxoplasma infection in the intestinal mucosa, others have examined the role of CXCR3 and its ligands in additional tissues and at different stages of infection." (PMID 24130498, 2013). "The results from this study, however, highlight the possible harm of inhibiting CXCR3-expressing cells into sites of inflammation during infection with an enteric pathogen." (PMID 24130498, 2013). "Our results establish a central role for CXCR3 in coordinating innate and adaptive immunity, ensuring generation of Th1 effectors and their trafficking to the frontline of infection to program microbial killing by inflammatory monocytes." (PMID 24130498, 2013). "There is evidence that CXCR3 expression enables T-cell entry into sites of infection, although the outcome of recruitment varies among pathogens." (PMID 24130498, 2013). "Expression of CXCR3 on cell surfaces was confirmed by flow cytometry with CD11c+MHCII+CD103+ DC isolated from the intestine of neonatal mice at the peak of the infection." (PMID 24367259, 2013). "To further validate CXCL10 as a candidate for the recruitment of CD103+ DC, we analyzed their recruitment in the intestine of CXCR3−/− neonates at the early stage of the infection (3 dpi)." (PMID 24367259, 2013). "Although IFN-γ, IL-10, and TNF-α responses remained intact in the MLN and spleen late during infection of CXCR3-deficient mice, a significant decrease in IL-12 production was observed in the MLN and spleen of Cxcr3−/− mice." (PMID 24130498, 2013).